ORAI1 (ORAI calcium release-activated calcium modulator 1)
Diseases named in the same sentence as ORAI1 in open-access papers (continued):
Sharing a sentence is not in itself a finding about the gene and the disease.
cancer (continued). "For instance, ORAI1 plays a role in entosis in cancer development via the septin-ORAI1-Ca2+/CaM-myosin light chain kinase (MLCK)-actomyosin axis." (PMID 38510751, 2024). "Cross‐referencing these datasets identifies NCX1, TRPC1, TRPC5, TRPM7, TRPM8, TRPML3, ORAI1/STIM1 and IP3R1 as cancer‐associated Ca2+ transporters regulated by S‐acylation via known enzyme(s)." (PMID 39429488, 2024). "Downregulation of ORAI1 can protect cancer cells from apoptosis induced by several reagents, such as thapsigargin, oxaliplatin and tumour necrosis factor α." (PMID 39539289, 2024). "Remodeling of calcium signaling via SOCE actively contributes to EMT, with amplified ORAI1 expression in cancers promoting this transition." (PMID 38672434, 2024). "The inhibition of cancer cell migration from istaroxime was further enhanced by blocking ORAI1 and FAK with the corresponding inhibitors." (PMID 38903530, 2024). "Orai1 regulates multiple signaling pathways in cancer cells by regulating the influx of Ca2+ from the extracellular space." (PMID 37759164, 2023). "Orai1 plays important roles in regulating physiological and pathological functions via Ca2+ in cancers." (PMID 37759164, 2023). "There are many reports about the messenger ribonucleic acid (mRNA) transcription and protein expression of Orai1 in various cancer cells." (PMID 37759164, 2023). "In this review, we present multiple physiological functions of Orai1 in various cancer cells and cardiac fibroblasts, including our findings." (PMID 37759164, 2023). "We demonstrated that increased Orai1 expression is necessary and sufficient for tumor progression by promoting cancer stemness in OSCC." (PMID 37759448, 2023). "Examples for that are the Kv11.1/β1 integrin complex, selectively expressed in cancer cells, Kv10.1/Orai1/SPCA2, Kv10.1/Calmodulin, Orai1/TRPC1/SK3." (PMID 37942486, 2023). "There are many reports that Orai1 regulates Ca2+ entry from the extracellular space and cell invasion in cancers." (PMID 37759164, 2023). "Silencing of Orai1 by shRNA decreased Ca2+ entry in human CRC cancer cells (SW620 cells) compared with control cells." (PMID 37759164, 2023). "Orai1 is undoubtedly an important molecule that plays a variety of roles depending on the cancer type." (PMID 37759164, 2023). "The latest research has found that PD-L1 is also expressed on sEVs in some cancers, and inhibiting PD-L1 on sEVs through the Ca2+ channel ORAI1 induced anti-cancer responses." (PMID 38093355, 2023). "Among the three Orai homologs, Orai1, the most studied homolog, was reported to play a critical role in cancer progression." (PMID 37759448, 2023). "These anaphylatoxins play a role in regulating inflammation, enhancing cell stemness, and activating the CRAC (Ca2+ release-activated Ca2+) channel ORAI1, a potential contributor to cancer progression." (PMID 37834179, 2023). "Taken together, Orai1 is one of the most important molecules for regulating SOCE in various cancers." (PMID 37759164, 2023). "Recently, more and more evidence is indicating that Orai1′s two homologs, Orai2 and Orai3, play a role in the development of different types of cancer such as lung, breast, prostate, and leukaemia." (PMID 37259313, 2023). "Taken together, Orai1 is abundantly expressed in various cancer cells, pancreatic stellate cells and cardiac fibroblast cells." (PMID 37759164, 2023). "All these cancer-related Orai1 mutants have been reported to lead to constitutive activity independent of STIM1." (PMID 36612099, 2022). "In other cancer types, enhanced Orai3 expression increased Orai1/Orai3 heteromeric formation and thus reduced the number of functional Orai1 channels." (PMID 36612099, 2022). "They reported that knockdown of Orai1 protected cells from apoptosis induced by TNFα or Cisplatin whereas Orai1 rescue re-established the normal rate for apoptosis in these cancer cells." (PMID 35821821, 2022).
cancer (continued). "The overexpression of Orai1/STIM1 was paralleled by the enhancement of Akt1, a serine/threonine kinase implicated in cancer cell proliferation, inhibition of apoptosis, and establishment of therapy resistance." (PMID 35207698, 2022). "In contrast to healthy human breast, colon and prostate tissue cells, which only express Orai1, analogous cancer cells, co-express SK3 and Orai1." (PMID 35327543, 2022). "The most extensively studied interplay of KCa2+ channels, in terms of structural and functional requirements and their role in cancer, represents that of Orai1 and SK3." (PMID 36612099, 2022). "In particular, for SK channels as well as their interplay with STIM1/Orai1, the detailed links to various cancer signaling pathways are insufficiently described." (PMID 36612099, 2022). "We and others have previously shown that ORAI1 mediates SOCE in cancer cell lines and plays a role in proliferation and chemoresistance." (PMID 35628366, 2022). "Abnormal SOCE has been associated to a number of disorders, including cancer, and alterations in Orai1 glycosylation have been related to cancer invasiveness and metastasis." (PMID 36612199, 2022). "Future studies assessing the mechanism by which increased AKT activation enhances ORAI1-mediated Ca2+ influx will further define the role of ORAI1 as a therapeutic target in cancers with AKT hyperactivation." (PMID 36230716, 2022). "The expression of CACNA1H and ORAI1 was downregulated in KRAS-mutated cells, whereas CACNA1C was upregulated in all tested cancer cells." (PMID 35267511, 2022). "When these cancer cells were transfected with a dominant negative mutant of ORAI1, sphere formation and tumor development in xenografts were considerably inhibited." (PMID 36142596, 2022). "Future studies exploring therapeutic strategies to target PTEN-deficient or hyperactivated AKT cancers should consider this novel correlation between AKT activation and ORAI1-mediated calcium influx." (PMID 36230716, 2022). "This review lays out the current state of knowledge of Ca2+-signaling effectors and proteins as potential targets for the treatment of certain cancer types, with Orai1 and SK3 presented as emerging therapeutic targets." (PMID 36612099, 2022). "This is a significant observation, as we investigated miR3653 expression in Huh-7 HCC CSC cells by enhancing STIM1 and Orai1 expression, which mimics poor cancer prognosis, instead of using parental EpCAM(-)/CD133(-) Huh-7 cancer cells." (PMID 36556285, 2022). "Another study suggested heteromeric Orai1/Orai3 channel formation, whereby Orai3 expression is downregulated in cancer, thus altering the Orai1/Orai3 ratio." (PMID 36612099, 2022). "All of these studies demonstrated that overexpression of STIM1 and Orai1 conferred chemoresistance to a number of cancers." (PMID 35207698, 2022). "A shift in the Orai1:Orai3 expression ratio increases SOCE, as well as the levels of cancer stem cell markers, a mechanism potentially linked to the PI3K/Akt pathway." (PMID 36612099, 2022). "Orai3 is a calcium channel activated by Stim1 or Stim2,9 but in further studies, Orai3 interacted with Orai1 to form a heteromer was recognized in cancer cells for proliferation and decreased apoptosis." (PMID 36128650, 2022). "SOCE is involved in various physiological and pathological processes, and Orai1-mediated SOCE affects cancer progression." (PMID 36310590, 2022). "There is at present limited evidence showing that Orai1 can function as an oncogene or a tumor suppressor depending on the cancer type." (PMID 36310590, 2022). "On the one hand, siRNA treatment against ORAI1 as well as pharmacological SOCE blockers induce cell-cycle arrest in different types of cancer." (PMID 34831241, 2021). "Defective signaling mechanisms of the CRAC channel proteins (STIM1, Orai1) can lead to diseases such as severe combined immunodeficiency, thrombocytopenia, tubular aggregate myopathy, ectodermal dysplasia or cancer." (PMID 34360783, 2021).
cancer (continued). "Increasing evidence suggest that store-operated calcium entry (SOCE), mediated by the STIM1 and ORAI1 proteins, is a key player in regulating the pathophysiology of cancer." (PMID 34155535, 2021). "Ca2+ entry into tumor cells has been confirmed to be due to SOCE mediated by ORAI1 channels and this process in malignant tumors have fascinated many investigators, and thus the channels were already designated to “onco-channels”." (PMID 34055617, 2021). "According to these data, Orai2 upregulation in cancer cells was greater than that of Orai1 (1.2 vs. 1.7 for Orai1 and Orai2, respectively)." (PMID 35008277, 2021). "The variation in the expression of Orai1 and Orai3 upon the treatment with chemotherapeutic drugs has been reported in several cancer types." (PMID 34065942, 2021). "Accumulating evidence suggested that calcium release-activated calcium modulator 1(ORAI1), a key calcium channel pore-forming protein-mediated store-operated Ca2+ entry (SOCE), is associated with human cancer." (PMID 34055617, 2021). "In cancer cells, Orai1 and Orai2 expression is upregulated and modulates cell migration by regulation of the AKT/mTOR/NF-κB signaling pathway." (PMID 34768857, 2021). "In contrast, the inhibition of Orai1 via siRNA and reduced extracellular calcium decrease cancer cell proliferation and enhance the cytotoxicity of cytotoxic T-lymphocytes and natural killer cells to tumors." (PMID 34572386, 2021). "Some studies have shown that blocking SOCE by using a specific blocker or by applying siRNA that target ORAI1 can inhibit the migration, invasion, and cell movement of cancer cells." (PMID 34055617, 2021). "In contrast, cancer samples expressing Orai1 dramatically decreased in CRPC-adeno (4% of positive cases) and in CRPC-NE (21% of positive cases) when compared to CLC (64% of positive cases) (p < 0.0001 and 0.004, respectively)." (PMID 34204608, 2021). "ORAI1-mediated SOCE has been confirmed to regulate cancer cell proliferation and invasion, and it has been reported that ORAI1 has an effect on CRC cell proliferation, but the research on the role of ORAI1-mediated SOCE in CRC is limited." (PMID 34055617, 2021). "Functional studies have indicated the inhibition of STIM1 and ORAI1 in the metastasis of cancer cells." (PMID 33182378, 2020). "Despite solid evidence that the SK3/Orai1 interplay plays a significant role in cancer cell growth, several questions remain to be answered." (PMID 33333945, 2020). "It has been shown that Kv10.1 interacts with the calcium entry channel Orai1 in some cancer cell types." (PMID 32283712, 2020). "Synta66 is thus a valuable tool for the evaluation of the contribution of Orai1 channels to cancer cell progression." (PMID 33036292, 2020). "Store-operated heteromeric Orai1/Orai3 channels have been discussed in the context of aging, cancer, and immune cell differentiation." (PMID 32252254, 2020). "The SK3/Orai1/TRPC1 interplay is proposed to interplay with the SK3 channel to trigger SOCE-dependent cancer cell migration." (PMID 33333945, 2020). "Currently, the co-regulation of SK3 and Orai1 represents one of the best-studied examples for an interplay of two types of Ca2+-regulated ion channels in cancer." (PMID 33333945, 2020). "The downregulation of the ORAI1-based SOCE is associated with increased store independent calcium entry (SICE), promoting cancer cells proliferation via the Ca2+/calcineurin-dependent transcription factor." (PMID 32733237, 2020). "Downregulation of Orai1 in CTLs led to decreased Ca2+ signals and increased efficiency to eliminate cancer cells." (PMID 32062611, 2020). "This assumption is based on the effects of alkyl-ether lipids disrupting the SK3-Orai1 co-localization and moving Orai1 outside of lipid rafts, thus, reducing cancer cell migration." (PMID 33333945, 2020).
cancer (continued). "In renal carcinomas, the ORAI1 expression levels in cancer tissues were statistically higher than the levels in the adjacent normal parenchymal tissues, promoting cell proliferation and migration." (PMID 32733237, 2020). "Higher expression of Orai1 is observed in cancer stem cells-improved cell population, including tumor spheres and ALDH1HIGH population of OSCC." (PMID 32280305, 2020). "As STIM1 and Orai1 over-expression has been observed across a multitude of malignancies, they are inarguably among the most enticing drug targets in anti-cancer therapy." (PMID 32599788, 2020). "Ca2+ influx via Orai1 channels was reported to play a relevant role in the development of a number of cancer hallmarks, including cell migration." (PMID 31652779, 2019). "Several studies have explored optimistic possibilities of targeting STIM1 and Orai1-mediated Ca2+ signaling in cancer cells, as well as vascular endothelial cells, for therapeutics." (PMID 31252656, 2019). "We previously found that Orai1 is involved in FAK phosphorylation in cancer cells; therefore, we investigated the role of AC8 in FAK phosphorylation in MDA-MB-231 cells." (PMID 31652779, 2019). "Again, the significantly higher proliferation rate observed with STIM1-OE cells over that of EpCAM(+)CD133(+) cells overexpressing both STIM1 and Orai1 (present data) confirms the poor prognosis of several cancer types with overexpressed STIM1." (PMID 31366337, 2019). "Emerging studies demonstrated the importance of STIM1/Orai1-mediated SOCE in the context-dependent roles of autophagy in human cancers." (PMID 31252656, 2019). "Nevertheless, the inhibition of Orai channels should inhibit cancer growth, and thus, the blockage of Orai1 and 2 by H2O2 in the TME should inhibit cancer growth (see the Graphical abstract)." (PMID 30935064, 2019). "The functional importance of STIM1/Orai1-mediated SOCE in cancer cell proliferation was extensively studied." (PMID 31252656, 2019). "ORAI1 has been assessed in a variety of cancer models since its identification in 2006, and this has been comprehensively reviewed by other authors." (PMID 30754719, 2019). "Not only immune cells but also cancer cells change the Orai3 to Orai1 ratio, thereby changing the H2O2 dependence of Orai-based Ca2+ entry." (PMID 30935064, 2019). "For example, several cancers have been associated with upregulated expression of STIM1, STIM2, or Orai1 and increased SOCE." (PMID 29783744, 2018). "Orai1 promoted cancer cell migration/invasion, drug resistance and angiogenesis, three phenotypes of which are well known for CSC characteristics." (PMID 27259269, 2016). "Formation of this complex leads to the formation of lipid-raft Cav-1/Orai1/TRPC1 complex cooperating with SK3 to promote SOCE-dependent cancer cell migration." (PMID 27102434, 2016). "The protein STIM1 andtheTRPC1 and Orai1 channels have been shown to be Store-Operated Channels (SOC) regulating cancer cell migration." (PMID 27102434, 2016). "STIM1 and Orai1 have also been demonstrated to play a role in cell migration and invasion in numerous cancers." (PMID 27417567, 2016). "However, the underlying mechanism by which Orai1 regulates cancer progression remains unknown." (PMID 27259269, 2016). "The discovery of STIM1 and Orai1 as the molecular components of SOCE has greatly advanced our understanding of the pathophysiological roles of SOCE in cancer." (PMID 25481035, 2015). "The importance of store-operated Ca2+ entry (SOCE) and the role of its key molecular regulators, STIM1 and ORAI1, in the development of cancer are emerging." (PMID 26257076, 2015). "While genetic mutations in Orai1 or STIM1 were linked to immune disorders, skeletal muscle myopathy and heart hypertrophy, the functions of these genes in various types of cancer have fascinated many investigators." (PMID 25481035, 2015).
cancer (continued). "Growing body of evidence indicates that SOCE in cancer cells is mediated by Stim1, which relays the information relative to the drop in ER Ca2+ levels to cell periphery, where it binds to and activates Orai1, a highly Ca2+-selective pore-forming unit." (PMID 25126575, 2014). "Orai1 is therefore proposed as an effective biomarker of the prognosis for patients with this form of cancer." (PMID 24797725, 2014). "Carcinoma specimens were divided into two groups: those with high and those with low Orai1 expression according to IHC scores using a cut-off value of 4 (the median value)." (PMID 24797725, 2014). "Another issue to be considered is the wide distribution as well as the multiplicity of cancer hallmarks controlled by a given TRP or Orai1 protein which requires careful consideration of its therapeutic potential." (PMID 24204345, 2013). "Targeting the molecular components of SOCE, STIM1 and Orai1, is thus a promising approach to inhibit cancer cell migration and tumor metastasis." (PMID 23594099, 2013). "Accumulated evidence indicates that Orai1-mediated calcium signaling plays important roles in cancer metastasis." (PMID 22778704, 2012). "Interestingly, ORAI1 silencing in a zebrafish nasopharyngeal carcinoma metastasis model reduced cell exudation and inhibited cancer cell adhesion, thus leading to delayed attachment to the extracellular matrix (ECM) surface." (PMID 38672434, 2024). "SPCA2 knockdown in these cells impairs proliferation, reduces the in vitro formation of extracellular microcalcifications, and inhibits tumor generation in nude mice injected with MCF7 SPCA2-knowdown cells, indicating a critical role of this SPCA2/Orai1 interaction in cancer cell biology." (PMID 39303919, 2024). "The coordinated S‐acylation of Orai1 and STIM1 by zDHHC and APT enzymes might recruit both proteins to the same lipid domain to optimize Ca2+ fluxes, as suggested by studies linking enzymes involved in STIM‐ORAI1 S‐acylation/de‐acylation and cancer." (PMID 39429488, 2024). "In addition, while this study focused primarily on the muscle phenotype of GS mice, ORAI1 is expressed and plays important roles in many other cell types (e.g. immune cells, platelets, neurons, and cancer cells)." (PMID 39420094, 2024). "Taken together, Orai1 coordinates various molecules in cancers." (PMID 37759164, 2023). "Fluorescence imaging shows rapid inhibitory effects of extracellular Zn2+ on Orai1-mediated SOCE accompanying intracellular Ca2+ oscillation through zinc binding with specific regions of outer Orai1, suggesting that zinc can inhibit cancer cell proliferation by preventing hyperactive Ca2+ signaling." (PMID 38069357, 2023). "To date, many reports have explored the role of Orai1 in cancer." (PMID 37759164, 2023). "Similarly, AM has been shown to inhibit the activity of other ion channels expressed in immune cells, including ORAI1, Kv1.3, and KCa3.1, some of which are also involved in cancer cell proliferation." (PMID 36769377, 2023). "Therefore, it will be extremely important to understand the role of Orai1 for developing new cancer treatments." (PMID 37759164, 2023). "However, in several tumor cells, upregulation of one or more of the CRAC channel components, mostly STIM1 and Orai1, promotes the development of cancer hallmarks." (PMID 36612099, 2022). "Interestingly, in cervical, colorectal, and liver cancer, only STIM1 has been detected to be critical, and in esophageal cancer, only Orai1 has so far been detected as such." (PMID 36612099, 2022). "However Orai1 can also mediate cancer progression by regulating and driving different Ca2+ influx pathways that are independent of the filling state of intracellular Ca2+ stores." (PMID 35456011, 2022). "Moreover, elevated STIM1 and Orai1 expressions were thought to promote tumor cell proliferation in various cancers." (PMID 35669690, 2022).